CALR (calreticulin)
Diseases named in the same sentence as CALR in open-access papers (continued):
Sharing a sentence is not in itself a finding about the gene and the disease.
tumor (continued). "As for the phenomenological model, tumor cells can be converted into dying tumor cells when treated by chemotherapeutic agents, whereas dendritic cells become active after sensing ATP, HMGB1, CALR, and/or ANXA1." (PMID 33281620, 2020). "Some chemotherapeutic drugs, such as doxorubicin, not only kill tumor cells and thus release tumor antigens but also elicit the appearance of a set of danger signals including ATP, HMGB1 or calreticulin, which are released into the extracellular space or exposed at the surface of dying cells." (PMID 31990272, 2020). "It is important to note that this data is based on calreticulin mRNA levels in a tumor biopsy, without considering the subcellular distribution of calreticulin in cancer cells." (PMID 32456685, 2020). "To evaluate, whether calreticulin expression increases the phagocytic efficacy of CD47 mAb therapy, we cocultured MNNG/HOS tumor cells with bone marrow‐derived M1 macrophages in presence of doxorubicin, CD47 mAb, and combination treatment." (PMID 31376208, 2019). "We harnessed a retrospective cohort of primary (no = 152) and metastatic (no = 74) tumor samples from HGSC patients to investigate the CALR expression in relation with prognosis and function orientation of the tumor microenvironment." (PMID 31747968, 2019). "Incubation with ART does not induce calreticulin translocation to the plasma membrane of any of the examined tumor line cells." (PMID 30367436, 2019). "The release/exposure of DAMPs (calreticulin, HMGB1, ATP, IFN) by cancer cells dying after PDT stimulates the presentation of tumour antigens by dendritic cells and polarizes T cell response towards the production of IFN-γ, which are essential for anti-tumour immune responses." (PMID 31906092, 2019). "Both tumour models exposed to PALM rich in H2O2 showed a reduction in proliferation and an increase in calreticulin exposure and ATP release, suggesting the potential use of activated media as an inducer of immunogenic cell death via activation of the innate immune system." (PMID 30858524, 2019). "Altogether, these results demonstrate that CALR expression in both primary and metastatic lesions constitutes a strong prognostic biomarker for the identification of chemotherapy-naïve HGSC patients with favorable disease outcome upon tumor resection." (PMID 31747968, 2019). "While, not acting directly in concert, the phagocytic stimulation provided by RT-induced calreticulin can be enhanced by blocking the anti-phagocytic signal CD47 which leads to increased dendritic cell and macrophage activation and improved anti-tumor immunity." (PMID 30692991, 2018). "ICD promotes the release of damage-associated molecular patterns (DAMPs), involving surface exposure of calreticulin, ATP secretion, and passive release of high-mobility group box 1 (HMGB1), raising the possibility that, as signals of danger, DAMPs facilitate anti-tumor immunity." (PMID 30282948, 2018). "However, we observed a positive correlation between tumour levels of BOK and Calreticulin (p = 0.0072, two-sided Wilcoxon signed-rank test)." (PMID 29374142, 2018). "Accordingly, IHC of tissue microarrays showed that high miR-27a-expressing tumours frequently displayed a weak or absent membrane staining for MHC class I molecules and calreticulin; the staining was stronger in low miR-27a-expressing tumours." (PMID 26913609, 2016). "In drug-sensitive tumors, doxorubicin induces an immunogenic cell death, by promoting the plasma membrane exposure of the protein calreticulin (CRT), which activates the local dendritic cells (DCs) to phagocytize tumor cells and stimulates the subsequent expansion of anti-tumor CD8+ T-lymphocytes." (PMID 26980746, 2016). "This elevation of calreticulin levels on cancer cell surface appears to enhance its potential of promoting ICD, presumably by boosting their removal by antigen-presenting cells through phagocytosis pathways optimized for recognition of tumor antigens." (PMID 25692097, 2015).
tumor (continued). "Unlike with calreticulin, tumor-localized recombinant Hsp70 protein injection after PDT has no impact on therapy outcome (Korbelik, unpublished results)." (PMID 25692097, 2015). "Based on the presented results, the hypothesis to be tested is that the adjuvant treatment with calreticulin provides a supplement DAMP material and promotes phagocytosis of PDT-treated tumor cells enhancing the development of antitumor-immune response." (PMID 25692097, 2015). "However, treatment of cells with the combination of mL4-3 and L1-7(N) modulated tumor-cell phenotype, increasing the surface expression (either percentage or MFI) of CEA, MUC-1, ICAM-1, Fas, Trail-R1, Trail-R2, and calreticulin." (PMID 26579226, 2015). "Using the vaccine SCCVII cells treated with calreticulin or mitoxantrone alone without PDT had no significant impact on tumor growth rates compared to those with untreated tumors (not shown)." (PMID 25692097, 2015). "Given the tumor-promoting (e.g., BiP/GRP78, PDI) and tumor-opposing (e.g., calreticulin) activities of ER chaperones and oxidoreductases, current knowledge suggests more pinpointed approaches are needed to increase efficacy of ER-targeted cancer chemotherapeutic strategies." (PMID 25386408, 2014). "Knowledge of their immunological functions emerged with the observation that HSP70, HSP90, gp96, calreticulin, HSP110 and GRP170 isolated from tumor cells can initiate adoptive, tumor-specific T-cell responses and protective immunity, whereas those from healthy cells do not." (PMID 23300563, 2012). "A number of mammalian HSPs (gp96, HSP90, HSP70, calreticulin, HSP110, grp170), when isolated from tumor cells, have been shown to elicit tumor-specific immunity, and when isolated from virus-infected cells, have been demonstrated to elicit virus-specific immunity." (PMID 20146807, 2010). "We speculate that this may reflect a non-productive ICD phenotype, wherein tumor cells emit ICD-associated signals (e.g., calreticulin, HMGB1) but fail to initiate effective immune clearance due to a profoundly immunosuppressive microenvironment." (PMID 40909289, 2025). "However, CD47, an anti-phagocytic “do not eat me” signal, is often highly expressed on tumor cells, counteracting the effects of CALR." (PMID 40356601, 2025). "Furthermore, ferroptosis inducers can trigger ICD in tumor cells, leading to the release of high-mobility group box 1 (HMGB1) and ATP into the tumor microenvironment, as well as the plasma membrane translocation of calreticulin (CRT)." (PMID 40636119, 2025). "Calreticulin is exposed to the plasma membrane as a DAME in early apoptosis and crosstalks with CD91 receptors in phagocytes, enabling them to ingest dead cells efficiently, resulting in subsequent cross-presentation of tumor antigen and tumor-distinct cytotoxic T lymphocyte responses." (PMID 38443363, 2024). "Given the vascular and tumor location of CALR/STC1, systemic administration may suffice but may not reach the infiltrating edge." (PMID 38786045, 2024). "Additionally, in the cell-death-rich region, the majority of the high-calreticulin cells were myeloid cells rather than tumor cells." (PMID 36672243, 2023). "Surprisingly, calreticulin was not significantly expressed on tumor bulk in any of the zones." (PMID 36672243, 2023). "This apoptotic effect on tumor cells could result in immunogenic cell death (ICD), characterized by the release of DAMPs such as calreticulin, heat shock proteins (HSPs), and adenosine triphosphate (ATP), which in turn trigger the activation of the antitumor immune response." (PMID 37242733, 2023). "RT can promote the release of new tumor antigens, calreticulin, and heat shock protein, and increased expression of major histocompatibility complex I (MHC I) can promote dendritic cell (DC) maturation and infiltration into tumor cells to activate the antitumor immune response." (PMID 37598158, 2023).
tumor (continued). "Additionally, the protein expression of CALR in KIRC from the CPTAC database was significantly increased in tumors compared with those in normal tissues and significantly increased with tumor grade." (PMID 36338983, 2022). "Moreover, the interaction between calreticulin and toll-like receptor 4 (TLR4) expressed on tumor cell surface promotes the secretion of TNFα and CCL19, which facilitates the migration and maturation of DCs, to limit the tumor progression in vivo." (PMID 36703971, 2022). "However, in MM cells engagement of CXCR4 by BoxA does not promote cell growth but rather induces the surface exposure of calreticulin and the depletion of surface CD47, tilting the balance of “eat me” and “don’t eat me” signals, and promoting tumor cell phagocytosis by macrophages." (PMID 33956406, 2021). "Unlike with surgical resection, the ablated tumor tissues are not removed, apoptotic or necrotic cells release damage-associated molecular patterns, such as HMGB1, ATP, ROS and calreticulin, which may serve to achieve in situ tumor vaccination." (PMID 33882892, 2021). "One of the main events that can be detected in the early stages of ICD is the translocation of calreticulin from the cytoplasm to the tumor cell membrane, which provides macrophage stimulation via the “eat me” signal that is antagonized by CD47 expressed on the tumor cell membrane." (PMID 34639014, 2021). "Immunostimulatory DAMPs include a release of endoplasmatic reticulum proteins like calreticulin and heat shock proteins (HSP), the toll-like receptor (TLR) 4 and TLR9 agonist high mobility group box 1 (HMGB1) and ATP, leading to DC recruitment and activation at the site of tumor cell death." (PMID 34025657, 2021). "ICD involves the cell surface exposure of calreticulin (CRT), release of DAMPs-related high mobility group box1 (HMGB1) and autophagy-dependent ATP release, which together, leads to the antigen uptake and presentation of DC cell, and then activates the CD8+ TILs to play the anti-tumor role." (PMID 34283088, 2021). "For instance, the absence of CALR might be compensated by the direct injection of recombinant CALR into the tumor or the administration of a CD47-blocking antibody, which neutralizes the main functional antagonist of CALR210,211." (PMID 33243969, 2020). "Furthermore, a calreticulin (CRT) signal that promotes phagocytic uptake of cancer cells by the immune system was upregulated in the FVIO plus AMF group, suggesting FVIO‐mediated hyperthermia induces tumor immunogenic properties." (PMID 32328428, 2020). "Quantification of Western blotting indicated that the expression level of calreticulin in 2D-PAGE/Western blotting was significantly higher in tumor tissues with metastasis than in those without metastasis (p < 0.05), with average differences of more than two-fold." (PMID 30974841, 2019). "However, because cisplatin does not provoke calreticulin exposure in tumor cells, cisplatin does not induce full-blown ICD." (PMID 29760371, 2017). "However, targeting GRP78 increased CD47 and calreticulin levels in normal mammary gland tissue, unlike tumor tissue." (PMID 28815041, 2017). "Some studies show that CALR and PDIA3 can translocate from the ER to the cell surface and facilitate tumor cell recognition and engulfment by dendritic cells and subsequent T-cell mediates elimination of the tumor, inducing the activation of adaptive immune responses in the tumor microenvironment." (PMID 29228584, 2017). "Increased calreticulin expression has been observed in various tumor-cell lines following in vitro and in vivo treatment with sublethal EBRT and proton radiation, and is believed to play a critical role in enhancing antigen-specific CTL recognition of tumor cells." (PMID 27893426, 2016).
tumor (continued). "In contrast to CALR, PS mediates clearance of tumor cells without activating an immune response." (PMID 26486085, 2015). "In addition, extracellular calreticulin but not ERp57 was required to induce phagocytosis and subsequent induction of anti-tumor immune responses." (PMID 25688334, 2015). "Moreover, CTL lysis increased when exogenous calreticulin was added to non-irradiated tumor cells, and increased even further when exogenous calreticulin was added to irradiated tumor cells." (PMID 24480782, 2014). "Western blotting analysis and immunohistochemistry of tumor tissues and normal tissues from patients with UTUC were carried out to further verify five possible UTUC biomarkers, including zinc-alpha-2-glycoprotein, calreticulin, annexin A2, annexin A3 and haptoglobin." (PMID 24884814, 2014). "Calreticulin was absent in > 70% of tumor cells, with only 2% expressing strong protein levels." (PMID 24480782, 2014). "However, no such difference was observed in the tumour to normal ratios of CALR, GRP78 or GRP94." (PMID 38353760, 2024). "Moreover, tumor PD-L1, PD-1, or PD-L1 im-munotherapy blockade activated NLRP3 leading to resistance in BC as reviewed by our research group, highlighting the fact that CALR/NLRP3 and PD-L1/sPD-L1 might provoke an immunosuppressive/resistance loop in BC." (PMID 37762557, 2023). "Interestingly, the mRNA of CALR was not consistently expressed in different tumor cells." (PMID 36386817, 2022). "Calreticulin is a calcium-sequestering protein with a known ability to block VDR signal transduction by interacting with its DNA binding domain, which may explain the lack of antiproliferative activity of calcitriol observed in our cultured endothelial cells and in tumor endothelium." (PMID 31698751, 2019). "Also, macrophages recognize pro-phagocytic signals, such as calreticulin and phosphatidylserine that are induced on tumor cells as a result of therapies such as chemotherapy and radiotherapy, which in combination with inhibition of the SIRPα/CD47 axis are shown to promote tumor cell uptake." (PMID 31801627, 2019). "Interestingly, this vaccination effect was independent of HSP90 expression and could be augmented by coating of melphalan-treated tumor cells with recombinant calreticulin, which was not otherwise detectable on the cell surface." (PMID 29209327, 2017). "In addition to greater CTL sensitivity, each tumor-cell line displayed some of the cardinal signs of immunogenic modulation following 223Ra therapy, such as upregulation of HLA-ABC and calreticulin, both of which are important for effective antigen presentation." (PMID 27893426, 2016). "However, this may not be the complete picture of tumor cell recognition, as calreticulin is also expressed to varying degrees on non-apoptotic cells." (PMID 25688334, 2015). "Moreover, we also provide the first glimpses that tumoural CALR levels might regulate phagocytosis in tumours, only in ICD but not non-ICD clinical settings." (PMID 26314964, 2015). "Finally, surface translocation of the ER resident protein calreticulin (together with ERP57) was shown to be an essential signal for efficient uptake of dying tumor cells by APCs and therefore a critical regulator of immunogenic cell death following tumor cell exposure to γ-irradiation." (PMID 23087904, 2012). "As such, unlike silent cell death, NDV triggers ICD, marked by calreticulin (CRT) exposure and DAMP release (e.g., HMGB1, ATP), effectively turning dying tumor cells into an “anticancer vaccine” and creating a bridge between oncolysis and immune activation." (PMID 41257772, 2025). "This study found that docetaxel enhanced CD8+ T-cell-mediated tumor cell killing but did not induce traditional markers of ICD such as ATP and HMGB1 but rather relied primarily on calreticulin translocation to the membrane." (PMID 39682260, 2024). "The absence of calreticulin or ANXA1, for example, is known to severely limit immune responses against tumor cells." (PMID 36015189, 2022).
tumor (continued). "We also identified six proteins (CALR, HIST2H2AC, HSPA5, P4HB, and PDIA6) in the HPA database that showed increased immunostaining in PCa tumor tissue, while low or not detected in normal prostate tissue." (PMID 33049715, 2020). "Tumor cell mitoses, CD68+ or CD163+ macrophages, CD47, calreticulin, or checkpoint molecules were not significantly different in these two groups." (PMID 30938231, 2019). "Post-PDT administration of calreticulin, one of the key DAMP molecules, enhanced tumor response in immunocompetent but not immunedeficient mice." (PMID 28218708, 2017). "The expression of CALR in NSCLC was not significantly related to the gender, age, tumor sizes, lymph node metastases, AJCC stages and pathological grades." (PMID 29228584, 2017). "Of note, the levels of calreticulin and HSP90 exposure were significantly higher in heat shock/γ-ray/UV-ray treated tumor cells from responders compared to non-responders." (PMID 25688334, 2015). "The expression of calreticulin gene was reduced in PDT-treated cells, while no changes were observed with the expression of this gene in tumor, liver, and spleen tissues in PDT-vaccine-treated mice." (PMID 25692097, 2015). "Hence, the capacity of Rb4 to lyse tumor cells in a non-physiological (unconventional) fashion may contribute to its pro-immune effects through the liberation of DAMPs such as HMGB1 and calreticulin." (PMID 35190586, 2022). "Therefore, we infer that CALR and PDIA3 exert a positive or negative effect on prognosis of patients with cancer by regulating the cancer cells themselves or the immune responses in the tumor microenvironment." (PMID 29228584, 2017). "In terms of efficacy, the simple delivery strategy of DAMPs to target tumor tissues may not be efficient because ICD induction depends both on the release of chemotactic agents and on the presence of recognition molecules, such as calreticulin, on the cell membrane surface." (PMID 36015189, 2022).